ZEB1 (zinc finger E-box binding homeobox 1)
Diseases named in the same sentence as ZEB1 in open-access papers (continued):
Sharing a sentence is not in itself a finding about the gene and the disease.
tumor (continued). "As expected from the expression of miR-200 family members, ZEB-1 is barely detected in epithelial cells suggesting that the downregulation of these miRs is an essential early step in tumor metastasis." (PMID 31417117, 2019). "Gene ZEB1 not only promotes tumor cell dissemination but is also necessary for the tumor-initiating capacity of pancreatic and CRC cells." (PMID 31792281, 2019). "Meanwhile, the recognized target genes of miR-101, such as c-Fos, ZEB1 and Mcl-1, known to promote tumor growth, were significantly decreased in AML cells transduced with sh-SNHG1." (PMID 31615767, 2019). "Other studies have shown that Nodal controls migration and invasion in several tumor types by modulating the expression of Snail, Slug and ZEB1." (PMID 31451106, 2019). "Mechanistic studies demonstrated that FOXO1-induced miR-200b expression through the GSK3β/β-catenin/TCF4 network-mediated stimulation of ZEB1, which reduced tumor stemness and the epithelial–mesenchymal transition (EMT) signal." (PMID 31754475, 2019). "In contrast, tumor cells that maintain the ZEB1 promoter in a repressed state are less likely to undergo the EMT." (PMID 31623163, 2019). "We observed that increased miR-142-5p level led to the reduced tumorigenic properties, such as migration and tumor sphere formation, and both observations were accompanied by the reduction of ZEB1 and SREBP1, and increase of E-cadherin." (PMID 31861383, 2019). "MiR-200/ZEB1 axis-related EMT is also associated with antitumor immunity suppression, with the EMT regulatory axis controlling PD-L1 expression on tumor cells." (PMID 30813457, 2019). "Acquisition of mesenchymal properties by tumor cells is associated with an upregulation of EMT transcriptional inducers such as TWIST1/2, SNAI2/SLUG, and ZEB1." (PMID 31075939, 2019). "In this report, we revealed that HIF‐1α and ZEB1 in the hypoxic tumor microenvironments would be new potential biomarkers for ACs and then the secondary induced TGF‐β to which EMT induction was dependent would be a critical clinical target for the AC therapy." (PMID 31674718, 2019). "ZEB1 is well-known as a transcription factor that promotes tumor invasion and metastasis by inducing the EMT in carcinoma cells." (PMID 31137914, 2019). "By recruiting co-suppressors or co-activators, ZEB1 was shown to either downregulate or upregulate the expression of target genes and promote tumor metastasis via EMT induction in cancer cells." (PMID 31137914, 2019). "Inhibition of ZEB1 expression by shRNA attenuated the collective invasion of tumor cell clusters with Ehi and E/M states and lung-colonizing ability significantly more than did GFP-shRNA." (PMID 31331982, 2019). "The target gene MIRLET7B promotes tumor cell proliferation and migration after positive regulation by TF ZEB1." (PMID 31126066, 2019). "In conclusion, this study identifies a novel association between stroma-adjusted ZEB1 expression and tumor immune activity and addresses the critical issue of confounding between EMT-associated genes and tumor stromal content." (PMID 31780722, 2019). "The considerably variable consequences of ZEB1 depletion observed in these transgenic lines are probably due to highly differential expression of ZEB1 in the tumour stromal versus epithelial compartments among different cancer types." (PMID 31324807, 2019). "Taken together, our observations highlight the potential role of miR-409-3p as a tumor suppressor in OS partially through down-regulation of ZEB1 and suggest that miR-409-3p has potential applications in OS treatment." (PMID 30846940, 2019).
tumor (continued). "It has been reported that ZEB1/BRG1 transcriptionally regulates E-cadherin expression and EMT that is implicated in the initial stages of tumor invasion." (PMID 31410208, 2019). "The fact that ZEB1 promoted EMT and facilitated tumor metastasis is probably the main underlying reason for this result." (PMID 30976202, 2019). "The signal network of ZEB1 involved in malignant transformation in various types of tumor is complicated." (PMID 30846940, 2019). "In this study, the miR-200/ZEB1 axis has PD-L1 as a downstream target with consequent immunosuppression in the primary tumor." (PMID 31531020, 2019). "Increased GSK3β expression stimulated the β-catenin/TCF4/ZEB1/miR-200b network, which increased the downstream tumor stemness and EMT signals." (PMID 31754475, 2019). "For example, Cul4A was reported to activate ZEB1 in tumor progression and tbx5 expression in zebrafish development by promoting H3K4 methylation." (PMID 31101894, 2019). "Given that ZEB1- pulmonary tumor emboli occur in mice in response to DCISCAF2cy, we reasoned that the mesenchymal trait in E/M tumor cells is down-regulated through MET during metastatic colonization." (PMID 31331982, 2019). "Inversely, the expression of ZEB1 was markedly upregulated in tumor tissues, and its mRNA level was negatively regulated by miR-126 expression in SiHa and Hela cells." (PMID 31007650, 2019). "While extensive evidence confirmed the importance of ZEB1 as an EMT transcription factor that promotes tumor invasiveness and metastasis, little is known about its regulation." (PMID 31828042, 2019). "Information obtained from a genetic pancreatic mouse model showed that EMT cells (Zeb1+) appear in precursor pancreatic intraepithelial neoplasia (PanIN) lesions and are able to generate heterogeneous tumours containing E-cadherin+ and E-cadherin− cells." (PMID 31091749, 2019). "Kaplan–Meier survival analyses revealed that PRMT1, ZEB1, nuclear grade, and tumor stage were significant prognostic factors in ccRCC." (PMID 31655611, 2019). "Treatment with both SDF-1 and TGF-β1 strongly up-regulates CAM6, E-cad, and ZEB1 expressions and enhances the Ehi and E/M tumor cell proportions in DCIS cells through Src, leading to increased collective invasion." (PMID 31331982, 2019). "Tumour budding cells in PDAC have been observed with increased levels of ZEB1 and ZEB2, and reduced levels of E-cadherin and β-catenin, indicative of EMP mediated local invasion." (PMID 31703358, 2019). "Collectively, ZEB1 is critical for the resistance of the SW1990/GEM cell-driven xenograft tumor to gemcitabine conferred by ROCK2." (PMID 31783584, 2019). "We have also shown induction of ZEB1 expression to generate the E/M state presumably by partially suppressing E-cad expression in CAF-primed tumor cells." (PMID 31331982, 2019). "Such Ehi tumor cells showed relatively strong membrane E-cad staining, whereas the E/M tumor cells exhibited more nuclear ZEB1 staining with attenuated E-cad expression." (PMID 31331982, 2019). "As CAF-primed E/M tumor cells apparently lead to collective invasion with Ehi tumor cells, we investigated the effects of ZEB1 expression on leader E/M tumor cells and metastasis in DCISCAF2cy." (PMID 31331982, 2019). "Zeb1 depleted tumours were better differentiated, indicating less local invasion, and showed significantly reduced metastasis when compared to control PDAC mice." (PMID 31703358, 2019). "We propose stratifying HCC patients according to ZEB1 expression, and treating patients with ZEB1-positive tumours with an UCN-01 containing combination therapy for a successful treatment." (PMID 31543517, 2019). "Uniquely, stroma-corrected ZEB1 expression was significantly inversely correlated with total immune cell abundance in all five tumor types." (PMID 31780722, 2019).
tumor (continued). "ZEB1 is best known for triggering an epithelial-to-mesenchymal transition (EMT) in cancer cells to promote tumor progression." (PMID 30910999, 2019). "It has been found that another interesting agent, mocetinostat inhibits ZEB1 expression and increases E-cadherin and miR-203 upregulation in Panc-1 cells as well as in hPaca1-derived tumor cells." (PMID 30691229, 2019). "We observed higher expression of ZEB1 mRNA and lower expression of miR-409-3p in tumor cell lines, when compared to normal cell line." (PMID 30846940, 2019). "Probing public databases ascertained a positive association of ZEB1 and PKCα expression in human HCC tumours." (PMID 31543517, 2019). "In contrast, overexpression of ZEB1 prevented gemcitabine-induced inhibition of tumor growth of the SW1990/GEM-shROCK2 cell." (PMID 31783584, 2019). "We stained the subcutaneous tumor sections with antibodies against E-cad, an epithelial marker, as well as ZEB1, vimentin and fibronectin, which are mesenchymal markers." (PMID 31331982, 2019). "Zinc-finger E-box binding homeobox 1 (ZEB-1) plays crucial roles in epithelial-to-mesenchymal transition during tumor carcinogenesis." (PMID 31248382, 2019). "Accumulating evidence indicates that the zinc-finger transcription factor ZEB1 is predominantly expressed in the stroma of several tumours." (PMID 31324807, 2019). "Zinc-finger E-box binding homeobox 1 (ZEB1) is a transcription factor that promotes tumor invasion and metastasis by inducing EMT in carcinoma cells." (PMID 30755599, 2019). "The down-regulation of various circRNAs targeting ZEB1 (circ-ZEB1.5, circ_ZEB1.19, circ_ZEB1.17, and circ_ZEB1.33) increased the level of miR-200, which promoted tumor lung metastasis." (PMID 31134126, 2019). "ZEB1 is a transcription factor that promotes tumor invasion and metastasis by inducing epithelial-mesenchymal transition (EMT) in carcinoma cells." (PMID 29423052, 2018). "A study of the Huh7 HCC cell line and 115 patient HCC tissue samples indicated that, during tumor progression, TANs upregulate the downstream ZEB1 transcription factors by secreting NE." (PMID 30157906, 2018). "Total mRNA was isolated from tumor cells treated with exosomes and qRT–PCR was performed to evaluate gene expression of Vimentin, N-Cadherin, Snail, Twist, Slug and ZEB-1 in recipient cells." (PMID 29854876, 2018). "One of the functional outcomes of the transition to a more mesenchymal state is an enhanced migratory behavior and previously ZEB1 was reported to induce tumor cell invasion and enhanced metastatic potential." (PMID 30174793, 2018). "This is compatible with ZEB1 being a pleiotropic transcription factor, and is supported by recent evidence that explains how ZEB1 contributes to tumor cell radioresistance by regulating homologous DNA recombination." (PMID 29744893, 2018). "Our further experiments showed that the epigenetic silencing of ZEB1 expression abrogated the ability of tumour cells to form tubular structures, while rescued ZEB1 expression restored the tubular structures in vitro or in vivo." (PMID 29754422, 2018). "Similar result was also shown in our in vivo study and depletion of ZEB1 protein in PC3 cells restrained growth of tumour cell xenograft in nude mice." (PMID 29754422, 2018). "We then evaluated the effect of ZEB1 knockdown on the regulation of tumour cell migration and invasion capacity." (PMID 29754422, 2018). "As a tumor suppressor, ZEB1 suppressed growth by increasing microRNA-200 targets to antagonize ERBB3, a driver of mutant EGFR-dependent cell growth." (PMID 32309604, 2018).
tumor (continued). "ZEB1 in particular invokes transcriptional reprogramming that drives EMT, and associated influences on tumour cell invasion, stemness and metastatic potential." (PMID 29871889, 2018). "Here, we showed that the transcription factor ZEB1, best known for promoting tumor progression, inhibits muscle atrophy and atrogene expression by antagonizing FOXO3-mediated induction of atrogenes." (PMID 30304480, 2018). "In the present study, we also found that the overexpression of CDK6 in human HCC tissues was due and correlated to the overexpression of a circulating RNA, circ-ZEB1.33, not only in the tumor, but also in the serum." (PMID 30123094, 2018). "We proved that RHBDD1 and ZEB1 were positively correlated at the protein level by western blotting and microarray assays in tumor tissues, which will further facilitate translational medicine research on RHBDD1." (PMID 29426364, 2018). "The authors concluded that these results confirmed a novel role for ZEB1 in ATLL as a tumor suppressor." (PMID 32309604, 2018). "qRT-PCR showed that the level of SNGH16 and ZEB1 in the tumor tissues derived from sh-SNHG16 transfected kyse-70 cells was significantly decreased, while the level of miR-140-5p was obviously increased." (PMID 29416674, 2018). "One of the most significant findings was that in gross total resections they observed a decrease in the percentage of ZEB1+ cells as they approached the invasive tumor edge challenging previous results which suggest the opposite occurs." (PMID 32309604, 2018). "Proliferation promotion roles of the circ-ZEB1.33-miR-200a-3p-CDK6 regulating axis are existed and verified in human HCC, both tumor and serum circ-ZEB1.33 can serve as an indicator for the prognosis of HCC patients." (PMID 30123094, 2018). "The addition of ZEB1 to age and tumor grade improved the ability to decide when to use procarbazine, CCNU, and vincristine in the treatment of patients with DG." (PMID 30705664, 2018). "The detection of serum circ-ZEB1.33 can reflect the CDK6 level in the tumor tissue, so we think serum circ-ZEB1.33 is a potentially valuable biomarker for HCC diagnosis." (PMID 30123094, 2018). "Circulating tumor cells (CTCs) have elevated levels of the key transcription factors ZEB1, SNAI1, and TWIST and their downstream targets." (PMID 29320425, 2018). "Decision curve analysis was performed to compute the net benefit of decisions to initiate chemotherapy with procarbazine, CCNU, and vincristine (PCV) based on the ZEB1 molecular marker along with age and tumor grade." (PMID 30705664, 2018). "A tumor suppressor role for ZEB1 in SS is further supported by our survival analysis showing a worse outcome for patients carrying ZEB1 homozygous loss." (PMID 30518749, 2018). "First, we focused on the miR-200 family, which has been recognized as a potential tumor suppressor via its inhibitory effects on Zeb1/2 expression." (PMID 30150766, 2018). "Quantitative PCR of cells isolated from primary tumor from knockout mice showed that mRNA levels of Zeb1 and Slug were decreased by 2-fold which is seemingly inconsequential functionally." (PMID 30456206, 2018). "The wound‐healing assay demonstrated that ZEB1 overexpression significantly induced LNCaP cell migration, while the Transwell invasion assay showed that the up‐regulated ZEB1 expression significantly enhanced tumour cell invasion capacity." (PMID 29754422, 2018). "We found that circ-ZEB1.33 overexpressed in tumor tissues compared to the adjacent tissues as well as normal liver tissues." (PMID 30123094, 2018). "By introducing a CRISPR‐Cas9‐mediated 30 bp deletion into the ZEB1 second exon, we observed reduced migratory and anchorage‐independent growth capacity of these tumor cells." (PMID 29744893, 2018). "We extracted total RNA from the mouse tumour tissues, and the qRT-PCR assay results suggested that the ZEB1 and Twist1 expression levels were reduced." (PMID 30518916, 2018).
tumor (continued). "Zeb1 is upregulated in several cancers, where it influences cell motility, cell cycle, and survival, and is an important contributor to tumor invasion and metastasis." (PMID 30580326, 2018). "Hsa-miR-150p is nodular-specifically overexpressed, and its target ZEB1 was significantly downregulated in nodular SGC suggesting a tumour suppressor role." (PMID 29760516, 2018). "An initial 334 diffuse glioma patients were assessed for ZEB1 copy number along with age, histological type and tumor grade." (PMID 30705664, 2018). "As increasing evidence is found for both the tumor suppressive and tumor promoter roles of microRNAs in cancer, there has been a push for further delineation of the role of ZEB1 and the miR-200 family." (PMID 32309604, 2018). "We further divided the HCC patients into two groups according to the expression of circ-ZEB1.33 in tumor tissues." (PMID 30123094, 2018). "In summary, circ-ZEB1.33 is a tumor promotion circular RNA, promoting HCC cell proliferation by enhancing the expression of CDK6 through sponging miR-200a-3p." (PMID 30123094, 2018). "Recently, the transcriptional network ZEB1/OLIG2/SOX2 has been shown to be crucial in GBM irrespective of driver mutations, playing an important role in tumor initiation, stemness properties, proliferation and tumorigenicity." (PMID 30158599, 2018). "This question can be addressed by mutating the miR-200 sites in the Zeb1 3′UTR, which we show here in two epithelial cancer models to be sufficient to induce EMT and have strong effects on tumor dedifferentiation, progression, and invasion." (PMID 30405106, 2018). "miR-200 also controls cytotoxic CD8p tumor-infiltrating lymphocytes, and the miR-200/ZEB1 axis also regulates the expression of PD-L1." (PMID 29723992, 2018). "Published studies indicated that ZFAS1 directly repressed KLF2 and NKD2 expression to promote tumor cell proliferation, and induced ZEB1 to enhance the epithelial–mesenchymal transition (EMT) and metastatic ability." (PMID 29678899, 2018). "Most of miR-200 tumour suppressor activity is obtained by direct targeting of the two zinc-finger E-box binding homeobox members Zeb1 and Zeb240–42." (PMID 29988033, 2018). "ZEB1 has been found to be correlated to a highly infiltrative tumor phenotype in both adult and pediatric high-grade glioma, partially in relation to hypoxia." (PMID 29164272, 2018). "For instance, it promotes tumor progression and metastasis through the miR-200a-3p/ZEB1 signaling pathway and promotes tumor angiogenesis in liver cancer through miR-107/E2F1/SPHK1 signaling." (PMID 29495592, 2018). "Our studies reveal a dose-dependence of miR-200c and exquisite sensitivity of Zeb1 regulation that critically impacts tumor differentiation and invasion phenotypes of a well-established tumor model of pancreatic-islet carcinoma." (PMID 30405106, 2018). "On the other hand, in contrast to the Snail1 and Twist1 knock-outs, ZEB1 knock-out suppressed the metastatic dissemination of primary tumor cells using the same KPC pancreatic cancer model." (PMID 30463358, 2018). "In various model systems, silencing of p21 increased mesenchymal features, including vimentin, fibronectin, N-cadherin, Slug, and Zeb1 expression, and increased tumor cell migration and invasiveness." (PMID 29774202, 2018). "Our networks showed a group of conserved associations between the miR-200 networks inferred from tumour and control data, this association core is conformed by miR-200 miRs and known transcription factors such as: TWIST-1, TWIST-2, ZEB-1 and ZEB-2." (PMID 29051564, 2017).